FAS (Fas cell surface death receptor)
Diseases named in the same sentence as FAS in open-access papers (continued):
Sharing a sentence is not in itself a finding about the gene and the disease.
tumor (continued). "Several FAS inhibitors, both natural and synthetic, have demonstrated anticancer activity by disrupting tumor cells’ lipogenic dependence with the FDA-approved drug orlistat (used for the treatment of obesity) being an example." (PMID 40426875, 2025). "DNase I administration affecting tumor size led to an increase in FAS+ population to 25.8 ± 8.9% in the RLS40Low/D and to 5.6 ± 1.5% in the RLS40Med/D subgroup." (PMID 40867260, 2025). "Quantification of FAS protein expression in the FL tumor cell population revealed lower expression in ARID1AMUT (N = 7) vs ARID1AWT (N = 36) FL." (PMID 39843653, 2025). "Quite unexpectedly, a significant increase in Pd-l1 mRNA level was observed, and, according to the flow cytometry results, DNase I treatment resulted in an increase in the number of neutrophils with potential anti-tumor phenotype (FAS+ and PD-L1+)." (PMID 40867260, 2025). "These effector T cells eliminate tumor cells by releasing cytolytic substances, such as perforin and granzyme, or by triggering apoptosis through the FAS‐FASL death signaling pathway." (PMID 40485603, 2025). "In this study, the mRNA level of the FAS gene increased significantly, indicating that autophagy inhibition removes the protective mechanism of tumor cells and promotes the activation of apoptotic signals." (PMID 40649969, 2025). "In LUAD, the median beta-value of FAS promoter methylation in normal tissue is 0.152 (range: 0.135-0.178), whereas the value in tumor tissue is 0.148 (range: 0.103-0.195)." (PMID 39416461, 2024). "The inhibition of the FAS expression can decrease the proliferation/growth of cancer cells, resulting in tumor apoptosis; therefore, FAS is considered a promising target for drug discovery." (PMID 38541630, 2024). "In conditions of preserved immunity, FAS-mediated apoptosis plays an important role in the elimination of tumor cells." (PMID 38791085, 2024). "Cytokine production in the specific tumor microenvironment, dominated by hypoxia and acidosis, supports tumor cell survival via FAS downregulation in tumor cells." (PMID 38791085, 2024). "Specifically, in gynecological malignancies studied to date, expression of FAS and especially FASL seems to be associated with tumor growth promotion and metastasis, as well as with a worse overall patients’ prognosis." (PMID 37382757, 2024). "Increased FAS gene expression is foreshadowed by hypoxia and acidification of the tumor microenvironment, the latter of which is the original intended target of ZIF-8." (PMID 39273239, 2024). "The results revealed that the LSD1 inhibitor SP-2509 sensitized neoantigen-expressing tumor cells to CAR-T cell therapy by releasing an antigen-independent killing signal through the FAS-FASL axis by inhibiting the H3K9me3 level of FAS." (PMID 39080807, 2024). "To confirm this proposal, we performed xenograft tumor formation assays with HCT116 cells and found that PIR KD dramatically retarded tumor formation and upregulated FAS expression accordingly." (PMID 38148593, 2024). "The combination of KRASG12Di MRTX1133 and immune checkpoint inhibitors can activate the FAS pathway, continuously inhibit tumor growth, enhance the ability to clear cancer cells, and improve survival outcomes." (PMID 38817907, 2024). "Tumor cells can become less sensitive to FAS-induced apoptosis by down-regulation of FAS receptors and thereby promote immune privilege that enables tumor growth and progression." (PMID 38791085, 2024). "FAS expression also decreased with tumor progression: low FAS was observed in 40.3% pTa, 44.6% pT1, and 53.3% pT2 cancers." (PMID 38791085, 2024). "In GBM, FAS expression is upregulated in tumors compared to non-tumor tissues, and lower FAS expression is correlated with better overall survival (OS)." (PMID 37741340, 2023).
tumor (continued). "This has led to studies targeting FAS for inhibition in tumor models, such as in ovarian cancer, where inhibition of FAS resulted in activation of the AMPK pathway and subsequent cytotoxicity in the SKOV3 human ovarian cancer cell line." (PMID 37908366, 2023). "Apart from lipid uptake, FAS and FAO also play critical roles in tumor-associated immune cells and serve as potential targets for combination immunotherapy." (PMID 37700339, 2023). "In contrast to normal cells, where the majority of free fatty acids are obtained from the diet and FAS activity is of little importance, tumor cells obtain the majority of their free fatty acids through FAS activity." (PMID 37908366, 2023). "CD8+ T cells as cytotoxic T lymphocytes play an essential role against virally infected and tumor cells via granule-mediated cytotoxicity, FAS-FASL interaction, and the release of cytokines (e.g. TNF-α and IFN-γ)." (PMID 36707896, 2023). "The most spliced gene was SNHG17 with >25 splice forms and tumour associated splice events of CD44, STAT1, FAS, and IRF1 further confirming the JAK-STAT pathway enrichment from GSEA." (PMID 37091785, 2023). "It plays a role in controlling tumor progression by transducing apoptotic signals to various organs through FAS-mediated apoptosis." (PMID 37513656, 2023). "Irradiation has been shown in various preclinical studies to alter tumor immune phenotype by augmenting the presence of MHC I on the tumor cell surface, improving expression of cancer-testis antigens and upregulating the FAS/CD95 complex." (PMID 37979032, 2023). "Initially, we identified FAS as a differentially expressed gene between unsupervised clusters of the tumor mRNA expression array data." (PMID 37569529, 2023). "Soluble GZMB and FAS were also found in tumor supernatants, but at lower levels compared to tumors obtained from mice treated with Th2 cells." (PMID 36376448, 2023). "IFN-γ can directly or indirectly induce tumor cell apoptosis by up-regulating the expression of FAS and DR5." (PMID 37254046, 2023). "Lymphocytes can directly interact with circulating tumor cells through the FAS-FASL axis or immune-checkpoint molecules, such as PD1-PDL1 and CTLA 4, which will induce immunosuppressive responses, leading to enhanced survival of the tumor cells." (PMID 37251953, 2023). "ICAM-1 promotes the adherence of T-cells to tumor cells and has been found to provide an alternative costimulatory signal that restores the cytotoxic function of CTLs, and FAS activates the caspase apoptosis pathway." (PMID 37754534, 2023). "ABCB1, BAX, BCL2, FADD, FAS, and several tumour protein families were identified as the genes responsible for such findings." (PMID 35884999, 2022). "Restoring FAS expression induced FAS receptor auto-oligomerization and tumor cell auto-apoptosis in metastatic human colon-tumor cells in vitro." (PMID 35053524, 2022). "To further determine the function of FAS in colon-tumor suppression, we used an experimental lung-metastasis mouse model by injecting CT26 cells into mouse-tail veins." (PMID 35053524, 2022). "Restoring FAS expression in metastatic mouse colon-tumor cells enabled FASL-induced elimination of FAS+ tumor cells in vitro and suppressed colon-tumor growth and progression in tumor-bearing mice in vivo." (PMID 35053524, 2022). "and Cyclinghigh tumor cells showed high expression of the cell-cycle signature, the cell growth/division signature, and the FAS/pentose phosphate signature." (PMID 36423636, 2022). "Taken together, we determined that restoring FAS expression in mouse colon-tumor cells is sufficient to render FASL-resistant metastatic mouse colon-tumor cells sensitive to FASL-induced apoptosis in vitro." (PMID 35053524, 2022). "CD8+ cytotoxic T lymphocytes (CTLs) are the primary immune cells that kill tumor cells via the FAS-FASL and perforin-granzyme pathways." (PMID 35053524, 2022).
tumor (continued). "It has been shown that tumor cells use an epigenetic mechanism, such as histone deacetylation, to silence FAS expression to evade host immune surveillance." (PMID 35053524, 2022). "Recently, FAS has been reported to have a tumor-promoting function in cancer stemness, proliferation, and metastasis, which is in line with our studies in OSCC." (PMID 35249111, 2022). "MUC1 and FAS displayed the most stable expression levels between the tumor and normal tissue, even though the expression level of MUC1 was higher than that of FAS." (PMID 35054482, 2022). "Results revealed that high FAS, TNFRSF14, TNFRSF17, TNFRSF1B, and TNFSF13B expressions are associated with a high probability of “hot” tumor." (PMID 36588791, 2022). "High levels of exogenous FAS were detected in the xenografts from mice treated with DOTAP-Chol-hFAS, indicating efficient delivery of the codon-usage-optimized FAS cDNA to the tumor site." (PMID 35053524, 2022). "We determined that ectopic expression of FAS is sufficient to sensitize colon-tumor cells to apoptosis induction in vitro." (PMID 35053524, 2022). "Apoptotic extracellular vesicles with FASL induces myeloma FAS-mediated apoptosis to suppress tumor growth in vivo." (PMID 35053524, 2022). "Consistent with the role of FAS in tumor cell apoptosis, emerging experimental data determined that FAS and other death pathways are essential for CAR-T cell efficacy." (PMID 35053524, 2022). "It is therefore reasonable to conclude that ectopic expression of codon-usage-optimized FAS results in high levels of FAS receptor on the metastatic tumor cell surface, which undergoes receptor auto-oligomerization and resultant auto-apoptosis in vitro." (PMID 35053524, 2022). "FAS is a death receptor expressed on the tumor cell surface, and its physiological ligand FASL is expressed on activated CTL and NK cell surfaces." (PMID 35053524, 2022). "HOXA9 and MEIS1 homeobox oncogenes (adjacent and coexpressed with miR-196b), along with FAS tumor suppressor, are direct targets of miR-196b and drive carcinogenesis in KMT2A-r cases in a bidirectional manner." (PMID 36010971, 2022). "To restore FAS expression in human colon-tumor cells, we synthesized human FAS cDNA with optimized codon use to maximize FAS protein expression." (PMID 35053524, 2022). "Exogenous restoration of FAS in CT26 cells rendered tumor cell sensitivity to FASL-induced apoptosis." (PMID 35053524, 2022). "The plasmid DNA was then used to transfect SW620 and LS411N cells, resulting in FAS expression in over 60% of tumor cells and a high level of FAS protein on the tumor cell surface." (PMID 35053524, 2022). "We determined that codon optimization results in high FAS expression in colon-tumor cells, and tumor-selective delivery of FAS cDNA nanoparticles is sufficient to suppress metastatic colon-tumor growth in vivo." (PMID 35053524, 2022). "CT26 cells express lower levels of FAS than the MSI subtype of MC38 tumor cells and are resistant to FASL-induced apoptosis." (PMID 35053524, 2022). "The regulation network revealed that LINC02195 positively regulates FASLG, which together with FAS initiates cell death and prevents tumor progression." (PMID 36425941, 2022). "Our data determine that tumor-selective delivery of FAS DNA nanoparticles is sufficient and yet safe for suppression of human colon-tumor growth in vivo." (PMID 35053524, 2022). "Despite these indirect functions, CD4+ T cells can eliminate tumor cells directly through the release of granzyme B and perforin and through the induction of apoptosis via FAS-FAS ligand." (PMID 35326515, 2022). "Decreased expression in FAS or increased expression of FASL have been detected in many cancers and been associated with aggressive tumor behavior." (PMID 33639675, 2021). "Monoclonal antibodies that act as a FAS agonist have also been developed as an alternative strategy to activate tumor cell killing via the FAS-FASL axis." (PMID 34771652, 2021).
tumor (continued). "For example, radiation is known to induce expression of NKG2DL, TRAIL-Rs, and FAS on tumor cells, thereby enhancing the recognition of malignant cells by NK cells and their sensitivity to killing." (PMID 34572108, 2021). "Although T cells were also sensitive to lower doses of the inhibitor (1.9–2.5 μM) to induce cell death, 0.5 μM SP-2509 did not impair cytokine release by CAR T cells and was sufficient to upregulate FAS at the tumor site." (PMID 34771652, 2021). "In contrast, an observation made in our study was an exclusive infiltration of CD3low Vγ9δ1 T cells in only RCC tumor tissues, and most of them were of the FAS+CD28-CD45RA+ TEMRA cells." (PMID 34071865, 2021). "FAS expression level is up-regulated in several cancers and exhibits a strong effect on tumor cell proliferation and apoptosis." (PMID 34335109, 2021). "In tumor cells, SAF transcription promotes the formation of the exon 6-skipped spliced variant of FAS pre-mRNA (FASΔEx6) by interacting with both the FAS pre-mRNA, predominantly at exon 5/6 and exon 6/7 junctions, and the human splicing factor 45 (SPF45)." (PMID 33799493, 2021). "For example, upon antigen recognition, CAR T cells produced proinflammatory cytokines, such as IFNG, which sensitized tumor cells to death receptor-mediated cell death by upregulating FAS expression." (PMID 34771652, 2021). "Our findings suggested that KDM1A-mediated FAS upregulation at the tumor site is the mechanism behind enhanced CAR T cell efficacy." (PMID 34771652, 2021). "Growth factor receptors interact and activate downstream PI3K/AKT/mTOR axis with subsequent transcriptional activation of FAS expression and it is critical for aerobic glycolysis and tumor growth." (PMID 33763366, 2021). "Once initial antigen encounter has upregulated FASL on a CAR T cell, it can subsequently kill FAS-expressing tumor cells even if they lack the target antigen." (PMID 34771652, 2021). "Previous studies have reported that a variety of tumors can downregulate FAS expression on the cell surface in order to escape a T cell-mediated tumor lysis via the FAS-FASL axis." (PMID 34771652, 2021). "Different chemotherapies have been shown to stimulate the expression of death receptors on the surface of tumor cells, including FAS (also known as CD95), and TRAIL-R1 and TRAIL-R2 (also known as DR4 and DR5) on a large panel of cancer cells." (PMID 34497771, 2021). "Next, to validate the transcriptomic findings, tumor samples were queried for FAS and FASL, both being known targets of miR-21, and both were notably induced by radiation in the miR-21−/− tumors at the mRNA and protein levels (p < 0.001)." (PMID 33672628, 2021). "On the other hand, epigenetic methylation at the promoter of the FAS death receptor in certain cancers reduces NF-κB-dependent activation of FAS expression, thus contributing to tumor cell survival by reducing levels of the proapoptotic FAS protein." (PMID 34440093, 2021). "To provide further evidence that FAS induction on the tumor cells was the mechanism responsible for enhancing the cytotoxic efficacy of L1CAM-specific CAR T cells, we conducted experiments to specifically block FAS activity." (PMID 34771652, 2021). "It has been reported that the activity of the FAS/FASL pathway is decreased in a variety of tumor stem cells and is related to poor prognosis and chemotherapy resistance in many tumors." (PMID 34033229, 2021). "Activation of the anti-proliferative STAT1 pathway by IFN-γ can lead to sensitization of tumor cells to FAS (CD95) and TRAIL resulting in apoptosis, and hindered tumor cell growth by inhibiting angiogenesis to induce a state of cellular dormancy." (PMID 34012451, 2021).
tumor (continued). "Cytokine changes and increases in cytotoxic activity, such as granzyme B and FAS expression, were evident, suggesting that G-CSF plays a role in both T helper and cytotoxic T cell activity in the tumor microenvironment." (PMID 33042110, 2020). "Surprisingly, we found that the tumor cells with higher FAS mRNA expression tend to be more sensitive to cabozantinib and erlotinib." (PMID 31942177, 2020). "The FAS–FASLG interaction has been shown to be a mechanism by which tumours can escape the immune system." (PMID 32606315, 2020). "We observed that FAS mRNA expression was correlated with the sensitivity of tumor cells to erlotinib (R^2=0.1; p=0.015; RC=0.32) and carbozantinib (R^2=0.068; p=0.047; RC=0.28), but not related with vemurafenib, dabrafenib, crizotinib and afatinib." (PMID 31942177, 2020). "Pharmacologic blockade of VEGF-A induced a marked increase in the influx of tumor-rejecting CD8+ T cells over Tregs that was dependent on attenuation of FAS antigen ligand expression and led to CD8-dependent tumor growth suppression." (PMID 33250900, 2020). "The decreased tumor size was associated with increased cytotoxic factor granzyme B and the apoptosis marker FAS in tumor tissue supernatants." (PMID 33042110, 2020). "PDNA-3 binding to FAS-1 deactivates the receptors and suppresses tumor cell growth and its distant metastasis." (PMID 32751068, 2020). "By averaging z‐score expression levels per tumor, tumors with DDR mutation had lower expression levels of CTLA‐4, IFNG, TNF, FAS, and VTCN1, and higher expression levels of IL6, IL1B, and IL12A compared with the DDR wild‐type ones." (PMID 31991061, 2020). "LinkedOmics database results showed that FAS (P = 4.623E-6) and hsa-miR-125b-5p (P = 1.102E-9) were significantly related to tumor purity and tumor stage of COAD." (PMID 32850813, 2020). "Granzyme B and perforin were examined as cytotoxic factors while FAS and Fas ligand (FasL) were examined as tumor apoptotic markers." (PMID 33042110, 2020). "Some studies have recently reported that FAS can serve as an oncogene that promotes tumor proliferation and maintains the stemness of tumor cells." (PMID 31942177, 2020). "One way that chemotherapies can sensitise tumour cells to immune-mediated apoptosis is by modifying the interaction between CD95 (FAS/APO-1) and its cognate ligand, FasL (CD178, CD95)." (PMID 30733494, 2019). "Exosomes secreted under hypoxic conditions also contained more STAT3 and FAS, which can be transferred to other tumor cells to promote tumor progression and metastasis." (PMID 30925917, 2019). "The combination of poly I:C and inactivated Sendai virus particles (hemagglutinating virus of Japan envelope; HVJ-E) increased the FAS+ neutrophil infiltration in the tumor." (PMID 31010242, 2019). "This corresponded with reduced numbers of OTI T cells in antigen-bearing tumours and upregulated FAS and PD-1 expression exclusively on remaining intratumoural, antigen-specific T cells." (PMID 29507342, 2018). "Our data suggests that FAS is one of the crucial factors that enhance tumor proliferation in ES, as well as other malignant tumors." (PMID 29563856, 2018). "Consistent with the data from in vitro experiments, xenograft ES models also indicated that miR-181c repression is capable of inhibiting ES tumor development in vivo following restoration of FAS expression and translation." (PMID 29563856, 2018). "Malignant tumor cells tend to downregulate FAS expression to avoid FAS-mediated apoptosis signaling." (PMID 29563856, 2018). "FAS plays a central role in programmed cell death and is important for regulating cell proliferation and tumor-cell growth." (PMID 28750683, 2017). "In TNBC, FAS was averagely expressed in 49% of tumor cells, whereas ER-positive subtypes showed an average Fas expression of 16-20%." (PMID 28121628, 2017).